ELK1 (ETS transcription factor ELK1)
Diseases named in the same sentence as ELK1 in open-access papers (continued):
Sharing a sentence is not in itself a finding about the gene and the disease.
cancer (continued). "Lastly, in order to know whether inhibition of ELK1 has similar effect on the cells upon UV irradiation as ZNF598 knockdown, we UV irradiated variety of cancer cell lines expressing ELK1 shRNA to different UV doses and measured their survival ability." (PMID 29464043, 2018). "The p-ELK1 expression levels tended to be elevated in muscle-invasive tumors, compared with non-muscle-invasive tumors, but they were not statistically different between low-grade and high-grade carcinomas." (PMID 29518027, 2018). "The role of Elk-1 in cancer cell formation has been progressively revealed over the past few years." (PMID 26824320, 2016). "In conclusion, ELK1 likely plays an important role in bladder tumorigenesis and cancer progression." (PMID 26342199, 2015). "Numerous studies have indicated that Elk-1 is involved in the progression of several cancers." (PMID 25326651, 2014). "Interestingly, several of these TFs (e.g., NKX3-1, SMAD1/3, SRF, ETV4 and ELK1) are known to play important roles in PCa, as well as in other types of cancer." (PMID 24968068, 2014). "Furthermore, we identified two cancer-specific Hh targets, ELK1 and MSX2, which have an essential role in tumour cell growth." (PMID 19107131, 2009). "Furthermore, we identified two cancer-specific Hh targets, ELK1 and MSX2, which have an essential role in GC cell growth." (PMID 19107131, 2009). "Even though there is limited data on whether some of these miRs indeed regulate ELK1 in all cancer types or whether each described mechanism is cancer-type-specific, the significance of this mechanism is great as these could be part of future therapeutic approaches." (PMID 40862737, 2025). "Furthermore, studies with forced overexpression of ELK1 confirmed that it can exert oncogenic potential, while conversely, several studies on ELK1-knockdown cancer cells report that its suppression or deletion effectively downregulates cell growth and promotes apoptosis." (PMID 40862737, 2025). "Interestingly, the three other proteins RXRA, BCL11A and ELK1 are also related to cancer." (PMID 27203237, 2016). "Interactions between ELK1 and CIP2A have been reported elsewhere as well, thus accrediting this mechanism with a pan-cancer significance." (PMID 40862737, 2025). "The interactions of ELK1 with MZF1, AR, and ER are some of the most reported in several cancer types, all credited with growth-related phenomena." (PMID 40862737, 2025). "Targeting ELK1-mediated transcription of CIP2A seems to have a pan-cancer significance, since it has been documented in several cancer types." (PMID 40862737, 2025). "In another study on BxPC-3 cells, ELK1 was found to promote the expression of MUC4, which is a pancreas-specific marker and also has been attributed with roles in cancer cell growth and metastasis." (PMID 40862737, 2025). "Analysing the top 100 co‐expressed genes of UBA1 in pan‐cancer on GEPIA2.0, the top 5 genes (CDK16, ELK1, KDM5C, RBM10 and TBC1D25) were highly correlated with UBA1 in most cancer types." (PMID 39183260, 2024). "The downregulated p-Elk1(Ser383) in this list was of particular interest, given that phosphorylation of this residue on Elk1 by activated ERK1/2 promotes proliferation of cancer cells." (PMID 35085550, 2022). "Other ETS family transcription factors, such as ETS proto‐oncogene 2 (ETS2) and ETS transcription factor ELK1 (ELK1), are also required for hypoxic induction of a subset of HIF‐2 target genes in endothelial cells and cancer cells." (PMID 34102031, 2021). "We align the sequence pairs for the coding sequences of the genes of BRCA1, ELK1, and CCDC91, which are related to cancer incidence –." (PMID 35402983, 2021). "A previous study showed that the transcription factor Elk-1 is a downstream target of Erk1/2 MAP kinases, regulating the migration of many types of cancer via its downstream targets including c-fos, EGR1, and PKCα." (PMID 34488769, 2021).
cancer (continued). "At the molecular level, monensin has pleiotropic effects affecting multiple cancer-related pathways such as the E2F/DP1, STAT1/2, NFκB, AP-1, Wnt, and Elk-1/SRF pathways, likely dependent on the cellular model." (PMID 32093282, 2020). "Existing evidences report that several key transcription factors contribute to the up-regulation of lncRNA in human cancers, such as SP1, ELK1, STAT3 and YY1." (PMID 31713587, 2019). "In this study, we also investigated the effect of monensin on multiple cancer-related pathways and found that monensin can inhibit E2F/DP1, STAT1/2, NFκB, AP-1 and Elk-1/SRF pathways." (PMID 30559409, 2018). "In the present study, we specifically considered the transcription factors Ets-like protein-1 (Elk-1) and myeloid zinc finger-1 (MZF-1), which regulate PKCα expression in cancer cells." (PMID 27542222, 2016). "Lapatinib indirectly inhibited CIP2A transcription by disturbing the binding of Elk1 to the CIP2A promoter and restoring PP2A activity, which led to p-Akt downregulation and cancer cell apoptosis." (PMID 26824320, 2016). "Taken together, the results suggest that the mechanism of afatinib in sensitive NSCLC cells is by decreasing CIP2A through a reduction in Elk-1 which restores PP2A activity and leads to p-AKT downregulation, thereby inducing cancer-cell apoptosis." (PMID 25537503, 2015). "Interestingly, although it was concluded from these analyses that TFPI1β may be required for tumor suppression, both TFPI1α and β induced the activity of cancer-driving transcription factors Elk-1, NF-κB, and the phosphorylation of AKT, highly suggestive of a role in cancer progression." (PMID 26501324, 2015). "In cancer cells, the active ERK1/2 protein will activate RSK2 and Elk1 proteins that subsequently activate c-Jun and c-Fos proteins." (PMID 23690850, 2013). "Elk-1 and JNK isoforms are known cancer-relevant genes that separately regulate important oncogenic pathways, including cell proliferation, apoptosis, and DNA damage pathways." (PMID 22852817, 2012). "It is noteworthy that ELK1’s “natural state” is a mostly inactivated one, and studies in transgenic mice (not in the context of cancer) have shown that its deletion does not severely affect embryonic development or adult life." (PMID 40862737, 2025). "miR-144 has been credited with multiple activities in cancer (both pro- and anti-oncogenic, depending on the cancer type), and its expression in SK-BR-3 cells was found to be regulated through GPER and the PI3K-MAPK/ELK1 axis." (PMID 40862737, 2025). "ELK1, a member of the TCF subgroup of the Ets oncogene family, is involved in various processes, including cell growth and differentiation, angiogenesis, and cancer, and functions as a transcription factor." (PMID 35892692, 2022). "ELK1 functions as a transcription factor and is a member of the ternary complex factor (TCF) subgroup of the E twenty-six (Ets) oncogene family, which is involved in various processes, including cell growth and differentiation, angiogenesis, and cancer." (PMID 35892692, 2022). "CD133, a widely-accepted Cancer Stem Cell (CSC) marker, was also shown to be regulated through ets motifs as well as hypoxia-inducible elements, through the interaction of HIF-1α and Elk-1 on the promoter." (PMID 33672811, 2021). "Indeed, analyses from the UALCAN database revealed that the expressions of SP1, ELK1, and EGR1 were remarkably aberrant in many TCGA cancer types." (PMID 35003212, 2021). "Indeed, ELK1 is involved in epithelial-mesenchymal transition in HCC, which is crucial for cancer cells to acquire chemoresistance." (PMID 34335929, 2021). "ELK1 may contribute to CD8+ T cell differentiation by activating the extracellular regulated protein kinases (ERK); this may help eradicate cancer cells by activating T cells." (PMID 32715641, 2020).
cancer (continued). "In muscle-invasive tumors, p-ELK1 positivity strongly correlated with cancer-specific survival (HR = 2.693, P = 0.021), whereas positivity of AR (HR = 2.280, P = 0.042), but not that of p-ELK1, was identified as a strong predictor for disease progression." (PMID 26342199, 2015). "The JNK interacting partner, Elk-1, is one of the critical downstream components of the Ras-MAPK pathway, but efforts to target this pathway using Ras or MEK inhibitors have failed to produce clinical benefits in CRCs and many other types of cancers." (PMID 22852817, 2012). "In the absence of NK1R, the matrix Nkx2-5_02 had a predominant participation driving 8 transcripts, which includes those involved in cancer (EYA1, Trail, HSF1, and ELK-1), smooth-to-skeletal muscle trans-differentiation, and Z01, a tight-junction protein, expression." (PMID 17519035, 2007). "Therefore, while PRP4K regulation of ELK1 demonstrates its role in connecting splicing and transcriptional machinery, there are potential unexplored clinical ramifications of the phosphorylation of ELK1 by PRP4K for both neurodegeneration and cancer." (PMID 35281802, 2022). "Similarly, ELK-1 and JNK isoforms are known separately as cancer relevant genes regulating important oncogenic pathways, such as cell proliferation, apoptosis, and DNA damage; however, their possible interactions and biological consequences in the context of CRC have not been reported." (PMID 22852817, 2012). "By contrast, moderate p-ELK1 expression was marginally or significantly associated with lower progression-free survival (PFS) (0/1+ vs. 2+, P = 0.055), overall survival (OS) (0/1+ vs. 2+, P = 0.020; figure not shown), and cancer-specific survival (CSS) (0/1+ vs. 2+, P = 0.008) rates." (PMID 29518027, 2018). "Kaplan-Meier and log-rank tests revealed that patients with p-ELK1-positive non-muscle-invasive and muscle-invasive tumors had significantly higher risks for tumor recurrence (P = 0.043) and disease progression (P = 0.045)/cancer-specific mortality (P = 0.008), respectively." (PMID 26342199, 2015). "Another study identified R-carvedilol, the enantiomer without β-blocking activity, as a potential mediator of cancer-preventive activity, since it successfully stimulates the RAS-RAF-MEK-MAPK pathway, without leading to ELK1 activation." (PMID 40862737, 2025). "Both Elk-1 and JNK have been established as important drug targets in cancer, though not in CRC, and have multiple drugs/inhibitors that are in various phases of clinical trials." (PMID 22852817, 2012). "However, the literature has showed that SERPINE1 is promoted, not inhibited, by the ETS family members, such as ELK1, Ets-1 and ELK3, in other cancer types." (PMID 26335051, 2015).
tumor (100 papers, 2012 to 2026). "In patient samples, multiplex fluorescent imaging showed that tumor cells expressed more 3βHSD1 and Elk1 in CAF-enriched areas compared with CAF-deficient areas." (PMID 37009898, 2023). "GADD45B-high tumor cells showed strong associations with transcription factors such as ELK1, PAX5, SMAD3, BACH1, and NR1H2." (PMID 37608794, 2023). "Elevated level of both 8-OHdG and p-ELK1 were positively correlated with loss of tumor encapsulation, microvascular invasion, poor tumor differentiation, and a higher TNM stage." (PMID 33522955, 2021). "q-PCR results showed that the YAP (Cyr61, Amotl2, and Ankrd1) and ERK1/2 target genes (c-Myc and ELK-1) were elevated in WISP2 deficient tumor samples." (PMID 32711570, 2020). "In addition, we found that GPX4 can be used as a new transcriptional target of ELK1, and the tumor progression caused by the overexpression of ELK1 can be attenuated by downregulating the expression of GPX4." (PMID 35962333, 2022). "Regarding ELK1’s role in tumor promotion, besides its activation via the RAS-RAF-MEK-MAPK pathway, significant insight is now available about the epigenetic regulation of its expression." (PMID 40862737, 2025). "In GBM, another study revealed that an isoform of the protein kinase family, Protein kinase C eta type (PKCη or PRKCH), contributes to tumor progression via activation of ELK1." (PMID 40862737, 2025). "Targeting ELK1 directly or indirectly is another major strategy in HCC, since ELK1 has been identified a major driver of tumorigenesis and tumor growth." (PMID 40862737, 2025). "The pro-tumor activity of hsa_circ_0000515 through ELK1 was evident in both CC tissues and cells, underscoring the importance of the circular-RNA as a potential therapeutic target, as well as that of miR-326 as a treatment strategy." (PMID 40862737, 2025). "A 2013 study reported that ELK1, as well as ETS variant transcription factor 4 (ETV4 or PEA3), regulates the expression of the tumor-suppressing microRNA miR-200b." (PMID 40862737, 2025). "In stem cells and tumor cells, ELK1 promotes proliferation, and inhibits apoptosis and differentiation; in the nervous system, it participates in processes such as long-term memory." (PMID 40666290, 2025). "Hsa_circ_0000515 was found to sponge miR-326 and thus increases in the circular RNA levels lead to increased tumor progression by ELK1 expression." (PMID 40862737, 2025). "In pancreatic cancer (PaCa), ELK1 has been found to regulate the expression of several genes contributing to tumor growth, invasiveness, metastasis, and chemoresistance." (PMID 40862737, 2025). "Another study showed that miR-597-5p can directly target and suppress ELK1 levels in PaCa, inducing apoptosis, and leading to tumor growth inhibition." (PMID 40862737, 2025). "Overexpression of miR-340-3p leads to tumor suppression, while mir-340-3p knocking-down leads to ELK1 overexpression and elevated proliferation, migration, colony formation, and invasion." (PMID 40862737, 2025). "ELK1 was found to be the target of the tumor-suppressor miR-29a-3p, which negatively regulated ELK1’s expression." (PMID 40862737, 2025). "The activity of MEKs, MAPKs, and ELK1 was found significantly suppressed and xenografts studies also revealed that tumor growth was limited as well, indicting a direct link between ELK1’s deactivation by EGFR blocking and antitumor effects." (PMID 40862737, 2025). "Another study focused on Parkin RBR E3 ubiquitin protein ligase (PRKN or PARK2), an E3 ubiquitin ligase with a known tumor-suppressing role and its interaction with ELK1." (PMID 40862737, 2025). "The transcription factor ELK1 is a substrate of ERK1, deacetylated ERK1 activates ERK1 activity, increasing ELK1 enzyme activity and thereby promoting tumour cell proliferation, migration and invasion." (PMID 39778006, 2025). "FUT1 has been reported to be a marker of tumor stemness, thus crediting ELK1 with a significant regulatory aspect in this context." (PMID 40862737, 2025).
tumor (continued). "One of these molecules is lncRNA TRPM2-AS which is regulated by ELK1 and whose overexpression was correlated to increased invasion and metastatic potential in GC cell lines and tumor tissues." (PMID 40862737, 2025). "ELK1 has been reported to be the target of several micro-RNAs, many of them are well characterized as tumor-suppressors." (PMID 40862737, 2025). "The study reported that by mediating YTHDF1’s overexpression, ELK1 is implicated in the expression of polo-like kinase 1 (PLK1), which promotes cell cycle progression and contributed to tumor growth and chemoresistance." (PMID 40862737, 2025). "Silencing leads to tumor suppression of in vivo models with a pattern similar to ELK1 silencing as reported in the same study." (PMID 40862737, 2025). "The transcription factor ELK1 is widely involved in tumorigenesis, tumor development, and drug resistance." (PMID 38397056, 2024). "These proteins are involved in mitosis either through regulation of metabolism, G1/S transition, or actin-tubulin dynamics, indicating a potential novel role for Elk-1 in mitosis in tumor cells." (PMID 38716144, 2024). "MiR-21 activates KRAS signaling via the transcription factor ELK1, promoting tumor cell proliferation, migration, and invasion." (PMID 39839479, 2024). "Multiplexed fluorescence staining showed that in primary tumor areas where CAFs were enriched, 3βHSD1 expression and Elk1 expression were increased." (PMID 37009898, 2023). "AR knockdown statistically significantly decreased FEN1, pho‐ERK1/2 and pho‐ELK1 expression in tumour tissues of nude mice as compared with the 22Rv1‐control group (all p < 0.001)." (PMID 37326412, 2023). "We further studied the effect of AR knockdown on AR, FEN1, pho‐ERK1/2 and pho‐ELK1 expression in tumour tissues by Western blot." (PMID 37326412, 2023). "Low NCOR2 mRNA expression is positively correlated with shorter OS in LUAD patients, and downregulating NCOR2 promoted the expression of the tumor factors ELK1 and AXL." (PMID 38077434, 2023). "ETs-like transcription factor 1 (Elk-1) is a nuclear transcriptional co-activator regulating the expression of ETs protein family genes, and the activation of Elk-1 is necessary for tumor progression." (PMID 36569303, 2022). "The knockdown of ELK1 inhibited tumor growth in nude mice and remarkably reduced the tumor weights and volumes." (PMID 34970415, 2021). "Our study identifies a new circular RNA, termed circ-PTPDC1 that is up-regulated in tumor tissues, cells and plasma of GC patients, and can act as a sponge of miR-139-3p to regulate the expression of ELK1." (PMID 34803498, 2021). "Patients with high levels of ELK1 and LGMN expression in tumor tissues experienced significantly shorter OS than patients with low ELK1 expression (n = 173, p < 0.0001)." (PMID 34966781, 2021). "The result of the present study showed that ELK1 expression in GC tumor tissues was statistically higher than that in their adjacent noncancerous tissues, which is consistent with the results in TGCA database." (PMID 34803498, 2021). "We propose that not only does ELK1 present a novel target for tumor therapy directed at eliminating BTIC population, but also can be used as a molecular diagnostic molecule to identify potential for tumor recurrence." (PMID 33672811, 2021). "Surprisingly, in our tumor series, miR-23a-3p expression was inversely correlated with ELK1 and CXCL8 expression and positively correlated with BMPR2 expression." (PMID 33800656, 2021). "CRC cell viability, colony formation, migration, and invasion significantly decreased in vitro by downregulating the ETS transcription factor ELK1 (ELK1) through sponging miR-330-5p by circ_000166, in addition to decreased tumor size and weight in vivo." (PMID 34829818, 2021). "In hepatocellular carcinoma, ELK1 was confirmed to enhance malignancy by promoting the epithelial-to-mesenchymal transition (EMT) of tumor cells through increasing the aPKC-1 levels." (PMID 34970415, 2021).